BRAF (B-Raf proto-oncogene, serine/threonine kinase)
Diseases named in the same sentence as BRAF in open-access papers (continued):
Sharing a sentence is not in itself a finding about the gene and the disease.
melanoma (continued). "Our study found that the concordance of known drug targets (mainly BRAF) during melanoma progression is higher than in previous meta-analyses, likely due to advances in molecular techniques." (PMID 38003476, 2023). "In the smaller diagnosis cohort, one melanoma case had a NRAS Q61R variant and the other case of melanoma had a BRAF V600E variant." (PMID 36125633, 2023). "Altogether, these results suggest that the overexpression of TERT was associated with increased resistance to BRAF and MEK inhibition in BRAF-mutated melanoma cell lines by a mechanism involving the reactivation of the MAPK pathway." (PMID 37296851, 2023). "The overexpression of miR-204-5p and miR-199b-5p inhibit melanoma cell growth in vitro, both alone and in combination with BRAF/MEK inhibitors (MAPKi), suggesting their antagonism of resistance." (PMID 37622997, 2023). "No direct comparison between adjuvant targeted therapy and immunotherapy for melanoma BRAF-positive patients has been performed." (PMID 37686659, 2023). "The prospective, non-interventional COMBI-r study assessed the effectiveness and tolerability of the BRAF-inhibitor dabrafenib combined with the MEK-inhibitor trametinib in patients with advanced melanoma under routine clinical conditions." (PMID 37760406, 2023). "To evaluate the invasive potential of Cdc42 and Cdc42(G12V) in BRAF mutant melanoma cells, we used a Matrigel invasion assay." (PMID 37114375, 2023). "In 2011, the FDA accepted the anti-CTLA4 immuno- and BRAF inhibitory targeted therapeutic modalities, which at last resulted in a breakthrough for the treatment of melanoma patients with poor expected outcomes." (PMID 37568785, 2023). "Experimental evidence indicates that BRAF-driven ER stress and unfolded protein response play an important role in melanoma." (PMID 37445731, 2023). "Patients with melanoma are identified as being BRAF + or −, which greatly impacts their treatment options." (PMID 37366925, 2023). "Targeting BRAF with small molecule inhibitors, such as dabrafenib and vemurafenib, is a successful therapeutic approach for melanoma." (PMID 38136350, 2023). "In patients with advanced mutant BRAF melanoma diseases, BRAFi like as vemurafenib or dabrafenib have been used successfully in conjunction with MEK (mitogen-activated protein kinase) inhibitors such as trametinib." (PMID 36747120, 2023). "Analysis by electron microscopy of several tumor biopsies from two BRAF-mutant melanoma patients enrolled in clinical trials for vemurafenib indicated a two- to six fold increase in autophagic vacuoles compared with baseline measurements." (PMID 37834222, 2023). "The inhibition of IL-1 receptor or CXCR2 signaling steps in association with the MAPK signaling pathway inhibition allows melanoma cells to overcome the resistance to BRAF inhibitors in vivo." (PMID 37174072, 2023). "Our findings demonstrate that 3a is an important antitumor candidate, and support further investigations to evaluate its potential for melanoma treatment, especially for refractory cases to BRAF/MEK inhibitors." (PMID 37259298, 2023). "BRAF V600E-targeted mono- and combination therapy is effective in BRAF V600E melanoma, but is ineffective against BRAF V600E colorectal cancer." (PMID 37760447, 2023). "In a retrospective study on melanoma LM with a historically low overall survival (OS) rate of just 2 months, the use of BRAF/MEK inhibitors or ipilimumab resulted in a significantly higher OS rate than the overall cohort (21.7 weeks vs. 6.9 weeks)." (PMID 38104104, 2023).
melanoma (continued). "Unlike melanomas harboring BRAF mutations, which are highly sensitive to MAPK inhibition (BRAF and MEK inhibitors; BRAFi, MEKi), BRAFi treatment of melanomas harboring wild-type BRAF (including NRAS-mutant) activates MEK/ERK and increases melanoma growth." (PMID 36765910, 2023). "Dabrafenib is a mutant BRAF‐specific inhibitor approved for melanoma and non‐small‐cell lung cancer." (PMID 36808802, 2023). "According to the four main melanoma genetic subtypes established by The Cancer Genome Atlas (TCGA), we found 52.8% (19/36) BRAF-mutant, 30.6% (11/36) NRAS-mutant, 8.3% NF1-mutant, and 13.9% (5/36) triple wild-type melanomas." (PMID 36901733, 2023). "Despite BRAF testing for advanced melanoma being compulsory based on unanimous international CPG, a generalized lack of awareness among stakeholders involved in melanoma decision making exists." (PMID 36998456, 2023). "It has been reported that HO-1 induction can promote cell proliferation through the BRAF-MAPK signaling pathway in melanoma." (PMID 37507910, 2023). "Chemoresistance presents a major challenge in melanoma therapy; hence, the effect of specific BRAF and MEK inhibitors in clinical use is limited and new therapeutical approaches are necessary." (PMID 37239024, 2023). "At the molecular level, targeting USP14 in melanoma increases oxidative and proteotoxic stress and subsequently triggers ROS-dependent and caspase-independent cell death that overcomes resistance to BRAF inhibitors." (PMID 36694209, 2023). "Targeting Skp2, combined use of Skp2 inhibitor and Skp2 degradation promoting drugs, was proved to be a solution to BRAF inhibitor resistance melanoma." (PMID 37089937, 2023). "As the RCT was conducted in the near future for patients with BRAF-mutant melanoma, future economic analyses should take adjuvant treatment as second-line treatment into account in the decision-making process." (PMID 36653848, 2023). "BRAF wild-type melanomas have been treated with monoclonal antibodies that target immune checkpoint proteins such as anti-PD-1 (programmed cell death protein-1) (like pembrolizumab or nivolumab)." (PMID 36747120, 2023). "The tumor-suppressive effect of GANT61 was shown to induce the apoptosis of melanoma cells and was described as effective against the resistance of melanoma cells to vemurafenib, an inhibitor of BRAF." (PMID 37240209, 2023). "The HDAC inhibitor ITF2357 targets oncogenic BRAF that is localised in both the cytoplasm and the nucleus of melanoma cells." (PMID 37298104, 2023). "Recently, PD-1 inhibitors for melanoma with toripalimab have been developed, and vemurafenib is a synthetic oral BRAF inhibitor." (PMID 37215493, 2023). "In the cBioPortal database, we found a frequency of 0.5–1.2% samples with CRKL and MAPK1 co-amplification with a trend to mutual exclusivity with KRAS, NRAS and BRAF mutations in NSCLC and melanoma." (PMID 37443114, 2023). "BRAF mutation, leading to the constitutive activation of this pathway, is notably involved in the process of oncogenesis of some melanoma, non-small cell lung cancer or colorectal cancer, for which BRAF inhibitors are validated in combination." (PMID 37760415, 2023). "Our rationale was that short-term exposure of melanoma cells to BRAF inhibitors leads to the significant induction of AR expression, accompanied by gene expression changes that, however, are insufficient to cause BRAFi resistance." (PMID 37838724, 2023). "Transfection of endothelial cells with mutant BRAF has been reported to increase VEGF secretion, while in melanoma cells pharmacological BRAF inhibition promoted vascular stabilisation via a presumed decrease in aberrant angiogenesis." (PMID 36539575, 2023). "Apart from the limited therapeutic success of BRAF/MEK inhibitors in melanoma patients, most patients exhibited treatment failure along with the development of acquired resistance." (PMID 37370757, 2023).
melanoma (continued). "TERT promoter mutations are the main mechanism for the continuous upregulation of telomerase in melanoma and co-occur frequently with BRAF alterations." (PMID 37296851, 2023). "Of note, treatment of Nrf2 depleted cells with BRAF or MYC inhibitor results in a higher survival rate of melanoma cells." (PMID 36747120, 2023). "In BRAF mutant D4M melanoma tumors, VEGFA/BRAF targeting reshaped the tumor microenvironment, largely by stimulating infiltration of M1 macrophages and CD8+ T cells, and sensitized tumors to immune checkpoint blockade (ICB)." (PMID 37183363, 2023). "A previous study has demonstrated that PI3K/AKT signaling can contribute to BRAF inhibitor resistance in melanoma." (PMID 37174072, 2023). "In this study, we established that Nox inhibition is a potential therapeutic strategy to combine with BRAF inhibitors in the treatment of melanoma patients, aiming to overcome drug resistance." (PMID 37189846, 2023). "Prospectively randomized trials showed improved recurrence-free survival (RFS) in stage III melanoma patients with adjuvant systemic therapy with immune checkpoint inhibitors (ICI) or BRAF/MEK targeted therapy." (PMID 36765660, 2023). "Immune checkpoint inhibitors and BRAF/MEK inhibitors are the cornerstone of treatment for melanoma; however, primary and acquired resistance to these therapies highlight an ongoing, unmet need to develop novel treatment modalities." (PMID 37370834, 2023). "Examples include adjuvant BRAF inhibitors in melanoma, osimertinib in resected NSCLC, and abemaciclib in breast cancer, with even more recent advancements seen in perioperative strategies across diverse histologies." (PMID 37888038, 2023). "Gowda et al30 assessed the nanoliposomal delivery of A2 inhibitor arachidonyl trimethyl ketone in melanoma treatment by using normal human fibroblast cell lines FF2441, BRAF melanoma cell lines, and random human melanoma specimens." (PMID 38022807, 2023). "MAPK pathway alterations have been identified across glioma subtypes, ages, and grades spurring several clinical trials following the success of BRAF inhibitors in melanoma." (PMID 37124503, 2023). "Since BRAF is a driver oncogene in melanoma, this suggests that anoikis resistance is a key feature of melanoma metastasis (Boisvert‐Adamo & Aplin, 2008)." (PMID 38162121, 2023). "Our findings support the utility of DDI assessment in melanoma patients treated with BRAF/MEK inhibitors." (PMID 37760556, 2023). "BRAF mutations drive constitutive activation of BRAF-MEK-ERK-MAPK signalling pathway (MAPK), which promotes melanoma cell proliferation and survival." (PMID 36678596, 2023). "In melanoma, NRAS mutations occur in 15 to 23.15% of tumors and are usually mutually exclusive with BRAF and KIT36." (PMID 36658200, 2023). "In 2015, researchers from the Cancer Genome Atlas Network (TCGA) classified melanoma into four major molecular subtypes: BRAF, RAS (N/H/K), NF1, and Triple-WT, with the first three subtypes resulting in a permanent activation of the MAPK/ERK." (PMID 37174072, 2023). "Peeper and colleagues showed that some melanoma cells treated with BRAF inhibitors become “addicted” to the drugs, such that drug withdrawal induces cell death." (PMID 36765910, 2023). "Four MEK inhibitors are meanwhile FDA approved to treat melanoma, neurofibroma, NSCLC and thyroid cancer in stratified patients with BRAF or KRAS mutations." (PMID 36675180, 2023). "In a Phase Ib upgrade/expansion study, LXH254 was evaluated in conjunction with trametinib among patients grappling with advanced/metastatic non-small cell lung cancer harboring KRAS or BRAF mutations and NRAS-mutated melanoma (NCT02974725)." (PMID 38111008, 2023). "However, BRAF mutations outside the V600 codon may occur in a small percentage of melanomas." (PMID 37569660, 2023).
melanoma (continued). "For example, concurrent to MSLT-II, landmark trials led to immune checkpoint blockade and BRAF/MEK inhibitors becoming the standard of care when adjuvant therapy was indicated for resected stage III melanoma in the setting of CLND." (PMID 36836846, 2023). "For BRAF-positive patients (up to 50% of malignant melanoma), effective treatment options are now available." (PMID 36680624, 2023). "As the mitogen-activated protein kinase (BRAF-MAPK) signaling pathway is frequently activated in melanoma, we analyzed TERT in melanoma subtypes with hotspot mutations in BRAF, RAS (NRAS, KRAS, HRAS) and NF1 genes in the SKCM cohort." (PMID 37418389, 2023). "Inhibition of the MAPK pathway with BRAF/MEK inhibitors reverses the switch in human melanoma cells." (PMID 37189846, 2023). "Molecular analysis has described BRAF mutations in the adult melanoma population, and a study highlighted BRAF testing and positivity in a pediatric melanoma cohort." (PMID 38136349, 2023). "Functionally, we found that TCF12 can enhance melanoma proliferation and metastasis, as well as sensitivity to BRAF(V600E)-targeted therapy." (PMID 37760480, 2023). "Here the authors identify a subset of BRAF treatment-resistant melanomas with suppressed PGC1a expression that are sensitive to HMGCR inhibitors." (PMID 37277330, 2023). "These have been stimulated kinases, like epidermal growth factor receptor (EGFR) in melanoma, B-Raf proto-oncogene, serine/threonine kinase (BRAF) in pulmonary cancer, and fms-like tyrosine kinase 3 (FLT3) in acute myeloid leukemia (AML) cases." (PMID 37062547, 2023). "While BRAF-targeted therapy is highly effective for melanoma, it is often ineffective against other cancers harboring the BRAF mutation." (PMID 38136350, 2023). "Nonetheless, the key DREAMseq study found that initial treatment with combination ICI therapy is significantly better than initial treatment with targeted therapy against BRAF and MEK, even in patients with BRAF-mutated melanomas." (PMID 37900283, 2023). "Similar results were observed after long-term follow up of BRAF mutant melanoma treated with a different BRAF plus MEK inhibitor combination, utilizing encorafenib with binimetinib." (PMID 37444637, 2023). "Agents such as trametinib or cobimetinib, that inhibit the activity of MEK1/2, the ERK1/2 upstream activating kinases, have been approved for patients with BRAF‐mutant melanomas." (PMID 37029785, 2023). "As a consequence, a phase Ib study has been conducted to test the MEK inhibitors pimasertib combined with voxtalisib in patients with advanced solid tumors, including TNBC and BRAFV600-mutant melanoma, who progressed on BRAF inhibitors." (PMID 36765661, 2023). "In GSDME-expressing melanoma, the combination of BRAF inhibitors and MEK inhibitors treatment, FDA-approved therapy for BRAF V600E/K mutant melanoma, activates caspase-3 and triggers GSDME pyroptosis." (PMID 36742298, 2023). "E2F1 is overexpressed in melanoma, and its inhibition initiates cell cycle arrest and apoptosis, as well as increasing the sensitivity of the melanoma cells to BRAF inhibitors." (PMID 38023136, 2023). "On the other hand, adhesion of BRAF mutant melanoma cells to ECM generated from MAF confers resistance to TT via the tyrosine kinase receptors for collagens DDR1 and DDR2 and activation of a NIK/NFkB2 survival pathway." (PMID 36774337, 2023). "For example, about 30% of patients develop MEK/ERK-independent resistance to BRAF inhibition in melanoma." (PMID 37834284, 2023). "Selective inhibitors of v-Raf murine sarcoma viral oncogene homolog B (BRAF), such as temozolomide and dacarbazine, and antibodies targeting T-lymphocyte-associated protein (CTLA4) have also been used in the modern melanoma therapies." (PMID 37242431, 2023).
melanoma (continued). "Combined BRAF and MEK inhibitors, as compared with BRAF inhibition alone, provided remarkable response rates in melanoma, delayed the emergence of resistance, and reduced toxic effects in patients with BRAFV600E-mutated melanoma." (PMID 37920169, 2023). "One of the main mechanisms triggering BRAF/MEK inhibitor-resistance in melanomas is activation of the Nrf2-pathway." (PMID 36678596, 2023). "We propose a mechanism whereby the inhibition of AKT2 impairs glycolysis and reduces an EMT-related gene expression signature in PTEN-null BRAF-mutant human melanoma cells to limit metastatic spread." (PMID 37894325, 2023). "With the discovery of additional melanoma driver genes, strong efforts were made to develop targeted therapies for BRAF wild-type tumors." (PMID 38003476, 2023). "RAF dimerization is also induced by first-generation BRAF V600E inhibitors in melanoma models, inducing the paradoxical activation of p-Erk1-2 in BRAF wild-type cultures." (PMID 36831331, 2023). "Mutations leading to activation of BRAF (BRAFV600 mutations) and NRAS occur in 50% and 15–20% of melanoma respectively." (PMID 36588164, 2023). "The inhibition of oncogenic B-raf by VMR has been shown to impair glucose uptake and glycolysis in BRAF-mutated melanoma." (PMID 37198319, 2023). "In this paper we shed light on the molecular mechanisms governed by a newly identified couple of oncomiRs, namely miR-4488 and miR-4443, in BRAF-mutant melanomas." (PMID 38008717, 2023). "For instance, data from CheckMate 067 support the use of anti-PD-1 plus anti-CTLA-4 over anti-PD-1 alone or anti-PD-1 plus anti-LAG-3 in patients with BRAF mutant melanoma." (PMID 37507765, 2023). "Concurrent treatment with CINN-EO enhanced the anti-melanoma effect of two conventional antineoplastic drugs: the mitochondria-targeting tamoxifen and the anti-BRAF dabrafenib." (PMID 36982774, 2023). "In case of advanced melanoma, molecular biology platforms perform targeted sequencing of certain exons of the BRAF, KIT and NRAS genes in the tumor DNA." (PMID 37936607, 2023). "Immunotherapy, including anti-PD-1 antibodies, is effective in BRAFV600E/K and BRAF-wild type (BRAFwt) melanoma." (PMID 37295047, 2023). "Within the past decade, targeted therapies (e.g., BRAF inhibitors or PD-1 immune checkpoint inhibitors) have greatly changed the landscape for the treatment of advanced melanoma." (PMID 37504313, 2023). "We showed that overexpression of TERT in a V600E-BRAF melanoma cell line drove resistance to BRAF and MEK inhibitors by a mechanism involving the reactivation of the MAPK pathway independently of telomere maintenance." (PMID 37296851, 2023). "To corroborate these clinical findings, we used the BRAF-mutant PDX melanoma model Mel006, which is particularly well-suited to study mechanisms of acquired resistance to targeted therapy in melanoma." (PMID 37072838, 2023). "A recent study evaluated the expression of six circulating miRNAs in serum samples derived from 70 BRAF-mutant melanoma patients as predictors of response to therapy prior to initiation of treatments." (PMID 37627054, 2023). "When BRAF-signaling is activated in melanoma, it downregulates the Wnt/β-catenin pathway, leading to inhibition of apoptosis in melanoma cells." (PMID 37235843, 2023). "BRAF/NRAS mutant melanoma cells activate the Nrf2 signaling pathway to protect cells against oxidative stress." (PMID 36747120, 2023). "A total of 165 patients with resected stage III and IV melanoma, eligible to adjuvant imunotherapy or anti-BRAF/MEK kinase inhibitors will be included." (PMID 37328818, 2023). "To strengthen these observations, we have analyzed nestin protein levels by IHC in an internal cohort composed of 14 BRAF-mutant melanoma patients whose biopsies have been collected before starting targeted therapies." (PMID 38008717, 2023).